TBX20 (T-box transcription factor 20)
Diseases named in the same sentence as TBX20 in open-access papers (continued):
Sharing a sentence is not in itself a finding about the gene and the disease.
colorectal cancer (4 papers, 2016 to 2025). A primary or metastatic malignant neoplasm that affects the colon or rectum. "Transcriptional downregulation in early colorectal cancer tissues due to hypermethylation of the TBX20 promoter is linked to poor prognosis in colorectal cancer patients." (PMID 38965548, 2024). "Previous study and our unpublished result demonstrated that TBX20 is a key tumor suppressor gene in colorectal cancer." (PMID 40889204, 2025). "The E3 ubiquitin ligase PDZ Domain Containing Ring Finger 3 (PDZRN3) mediates the ubiquitination and degradation of TBX20 protein in early colorectal cancer tissues." (PMID 38965548, 2024).
left ventricular noncompaction (4 papers, 2021 to 2025). Left ventricular noncompaction (LVNC) is a rare cardiomyopathy characterized anatomically by prominent left ventricular trabeculae and deep intratrabecular recesses causing progressive systolic and diastolic dysfunction, conduction abnormalities, and occasionally thromboembolic events. "These include MYBPC3 mutations in HCM, TBX20 (OMIM: 606061) mutations in left ventricular noncompaction (LVNC), and RAF1 (OMIM: 164760) mutations implicated in HCM associated with Noonan syndrome." (PMID 40507801, 2025). "TBX20 has been linked to congenital heart defects; although an association with left ventricular noncompaction (LVNC) and DCM has been proposed, it is still considered a gene with limited evidence for these phenotypes." (PMID 38353104, 2024).
myocardial infarction (4 papers, 2016 to 2025). Gross necrosis of the myocardium, as a result of interruption of the blood supply to the area, as in coronary thrombosis. "On the contrary, overexpression of Tbx20 promotes adult cardiomyocyte proliferation post myocardial infarction, thus highlighting its importance for proper heart development and function." (PMID 36805334, 2023). "Likewise, Tbx20 overexpression in adult cardiomyocytes promotes their proliferation and improves cardiac function after myocardial infarction through the activation of multiple pro-proliferation pathways, including BMP signalling." (PMID 29540665, 2018).
cervical cancer (2 papers, 2016 to 2021). A primary or metastatic malignant neoplasm involving the cervix. "QMSP was designed for 5 genes (GFRA1, SLC6A5, SOX1, SOX14, TBX20) and their diagnostic potential was evaluated on scrapings from a large series of cervical cancer patients (n=125: 57 ADC and 68 SCC) and controls with similar age." (PMID 27738327, 2016). "TBX20 methylation has previously been related to specific bladder cancers, late stage hepatocellular carcinoma development, recurrence of lung adenocarcinoma and cervical cancer." (PMID 27738327, 2016). "They identified 6 genes as the best candidate methylated biomarkers of cervical cancer progression (RGS7, LHX8, ST6GALNAC5, TBX20, KCNA3 and ZSCAN18)." (PMID 34882728, 2021). "Of the 53 differentially methylated candidates that were found in both ADC and SCC, 20 genes were described previously in literature as being more frequently methylated in cancer, and 6 genes in (squamous-cell) cervical cancer (SOX1, SOX14, ONECUT1 and WT1) or high-grade CIN (GFRA1, SOX1 and TBX20)." (PMID 27738327, 2016).
lung carcinoma (2 papers, 2013). "Overexpression of TBX20, which was also identified in this study, has been reported in lung cancer." (PMID 24369052, 2013).
Patent foramen ovale (2 papers, 2021 to 2025). Failure of the foramen ovale to seal postnatally, leaving a potential conduit between the left and right cardiac atria. "TBX20, for example, is essential for chamber formation; murine knockouts show severe cardiac malformations, while gain-of-function variants in humans are linked to ASD and patent foramen ovale 59,63,64." (PMID 40832351, 2025).
Autoimmunity (1 paper, 2022). The occurrence of an immune reaction against the organism's own cells or tissues. "As an essential factor of autoimmunity, TBX20 produces IgG2a via activation of B cells during viral infection." (PMID 35572639, 2022).
cardiac hypertrophy (1 paper, 2022). "However, TBX5, TBX20, ERBB4, and GRK5, which have been linked to the proliferation of fetal and neonatal cardiomyocytes [TBX5, TBX20, ERBB4] and cardiac hypertrophy [GRK5], were upregulated in the CM1 cluster, as well as in Fetal cardiomyocytes." (PMID 35860330, 2022).
channelopathies (1 paper, 2024). "TBX20 was sequenced by next-generation sequencing in 7463 unrelated probands with a diagnosis of DCM or LVNC, 22 773 probands of an internal comparison group (hypertrophic cardiomyopathy, channelopathies, or aortic diseases), and 124 098 external controls (individuals from the gnomAD database)." (PMID 38353104, 2024).
colon cancer (1 paper, 2023). "TBX20’s expression is curtailed due to hypermethylation of its promoter region in colon cancer, where it acts as a tumor suppressor." (PMID 37958445, 2023).
developmental delay (1 paper, 2013). "Thus, developmental delay is associated with the Tbx3 mutant genotype, even though Tbx20 mutants have a more severe and earlier heart abnormality." (PMID 23936153, 2013). "Among the embryos from Tbx20+/-; Tbx3+/- double heterozygous crosses at E8.5, some single or double homozygous embryos showed developmental delay, but over 90% were living (65/71); by E9.25, however, 37% (7/19) were dead." (PMID 23936153, 2013).
diabetes (1 paper, 2023). "The expression of Tbx20 was also increased significantly during diabetes (23.28 ± 3.5%) as compared with control (3.68 ± 1.5%)." (PMID 36805334, 2023). "The expression of tbx20 and bmp2 was also increased significantly during diabetes as compared with control." (PMID 36805334, 2023). "Thus, diabetes augments ER stress with concomitant increase in the expression of Tbx20 and Bmp2." (PMID 36805334, 2023).
diabetic cardiomyopathy (1 paper, 2023). Diabetic cardiomyopathy is a disorder of the heart muscle in people with diabetes. "In in vivo ER stress, as well as in diabetic cardiomyopathy, the activity of Tbx20 is increased with concomitant increased cardiomyocyte proliferation and decreased apoptosis." (PMID 36805334, 2023). "Diabetic cardiomyopathy also resulted in increased expression of Tbx20 (4.4 ± 0.5-fold) and Bmp2 (2.9 ± 0.5-fold) as compared with control group." (PMID 36805334, 2023). "In order to replicate our observations in a disease model, we looked in the expression of Tbx20 during hyperglycemia in vitro and diabetic cardiomyopathy in vivo." (PMID 36805334, 2023). "We have also reported an increase in the activity of Tbx20 and Bmp2 during hyperglycemia in vitro and diabetic cardiomyopathy in vivo with concomitant increase in cardiomyocyte proliferation." (PMID 36805334, 2023).
esophageal cancer (1 paper, 2021). A primary or metastatic malignant neoplasm involving the esophagus. "Our results showed that knockdown of TBX20 may have led to a striking defect in esophageal cancer cell growth and carcinogenesis-related pathway, including cell cycle and homologous recombination." (PMID 34381055, 2021).
Hyperglycemia (1 paper, 2023). An increased concentration of glucose in the blood. "Prolonged hyperglycemia caused augmentation of ER stress with concomitant decrease of Tbx20–Bmp2 signaling, decrease in cardiomyocyte proliferation, and increase in cardiomyocyte apoptosis." (PMID 36805334, 2023). "The expression of Tbx20 and Bmp2 also increased with concomitant increase in cardiomyocyte proliferation upon induction of hyperglycemia." (PMID 36805334, 2023). "Thus, Tbx20–Bmp2 signaling imparts protection against hyperglycemia by augmenting cardiomyocyte proliferation." (PMID 36805334, 2023). "However, when the expression of Tbx20 is decreased during ER stress or during hyperglycemia, the ROS levels were increased significantly and was almost equal to that of positive control, thus corroborating the role of Tbx20 in limiting ROS generation during ER stress." (PMID 36805334, 2023).
ostium secundum atrial septal defects (1 paper, 2021). "A gain-of-function mutation in the TBX20 gene (p.I121M) was found in a patient with ostium secundum atrial septal defects (ASDII) and in his sister and mother, both affected by large PFOs." (PMID 34946902, 2021).
Patent ductus arteriosus (1 paper, 2023). In utero, the ductus arteriosus (DA) serves to divert ventricular output away from the lungs and toward the placenta by connecting the main pulmonary artery to the descending aorta. "The DNA methylation of seven CpG sites in the TBX20 gene promoter was analyzed through pyrosequencing as a quantitative method in 48 patients with congenital septal defects and 104 individuals with patent ductus arteriosus (PDA)." (PMID 36831251, 2023).
skin cutaneous melanoma (1 paper, 2023). "Among skin cutaneous melanoma cases, TBX20 was detected with missense and splice mutations at a frequency of 5.63% (25 cases), which is the highest alteration frequency among the PanCancer Atlas based on data obtained from the TCGA database." (PMID 37854190, 2023).
thoracic aortic aneurysm (1 paper, 2025). An aneurysm formed in the wall of the proximal portion of the descending aorta proceeding from the arch of the aorta. "This study suggests that deleterious TBX20 variants predispose to BAV/thoracic aortic aneurysm, though the functional effects of these variations remain to be expounded." (PMID 40075846, 2025).
heart disease (6 papers, 2017 to 2025). "Determining how abnormalities of the Tbx20-TLE complex contribute to adult-onset heart disease and identifying mutations in the TLE/Gro complex associated with cardiovascular disease will be crucial for assessing the function of the Tbx20-TLE interactions in additional disease states." (PMID 37756602, 2023).
tumor (5 papers, 2013 to 2025). "In xenograft models, both HS and β‐sitosterol treatments inhibited tumor growth and upregulated TBX20 protein expression, with β‐sitosterol demonstrating a stronger effect." (PMID 40889204, 2025). "We have not only found that high expression of TBX20 is related to the poor prognosis of patients but also we verified the critical role of TBX20 in tumor growth in vivo." (PMID 34381055, 2021). "DNA hypermethylation of the ADCY5, EVX1, GFRA1, PDE9A, and TBX20 genes resulted in reduced mRNA expression in tumorous tissue samples." (PMID 23544068, 2013). "In conclusion, β‐sitosterol, as an anti‐tumor active component of HS, prevents CRC cell proliferation, and accelerates apoptosis by upregulating TBX20." (PMID 40889204, 2025). "The inhibitory effect of TBX20 on tumor growth occurs through the suppression of non-homologous DNA end-joining (NHEJ)-mediated DNA repair in CRC cells." (PMID 38965548, 2024). "TBX20 inhibits the recruitment of Ku70 and Ku80 to the chromatin of CRC cells, inhibiting NHEJ-mediated double-strand break repair, thereby suppressing cell proliferation and tumor growth." (PMID 38965548, 2024).
cancer (3 papers, 2016 to 2022). A tumor composed of atypical neoplastic, often pleomorphic cells that invade other tissues. "The top pathways upregulated by Tbx20 KD involved IL-17 and relaxin signaling, as well as transcription misregulation in cancer." (PMID 35293863, 2022). "Except for TBX5, all 5 genes (GFRA1, SLC6A5, SOX1, SOX14 and TBX20) were significantly differentially methylated between normal and cancer tissues with a high methylation frequency in both ADC and SCC." (PMID 27738327, 2016). "We also found that the overall survival of 563 patients with TBX20 mutation was worse than 18,632 patients without TBX20 mutation in TCGA Pan-Cancer Resource (P = 9.04 × 10−4, log-rank test)." (PMID 34381055, 2021). "In the second diagnostic evaluation 229 scrapings were analyzed for SLC6A5, SOX1, SOX14 and TBX20 hypermethylation using the QMSP threshold values that were set in the normal and cancer samples." (PMID 27738327, 2016).
neurodegenerative disease (1 paper, 2022). A disorder of the central nervous system characterized by gradual and progressive loss of neural tissue and neurologic function. "The results of the present study showed that Tbx20 was positively correlated with CCL1, suggesting that Tbx20 could regulate immunity and participate in the development of neurodegenerative diseases." (PMID 36279395, 2022).
TBX20 also shares sentences with these, for which no sentence is quoted: atrial fibrillation (3 papers); coronary artery disease (2); infection (2); mitral valve disease (2); aortic coarctation (1); atrioventricular septal defect (1); bladder cancers (1); cardiac tumors (1); cardiovascular disease (1); congenital atrioventricular block (1); congenital heart malformations of (1); double outlet right ventricle (1); Epileptic encephalopathy (1); familial bicuspid aortic valve (1); hepatocellular carcinoma (1); hypertrophic cardiomyopathy (1); hypoplastic right heart syndrome (1); Intellectual disability (1); Left ventricular noncompaction cardiomyopathy (1); long QT syndrome (1); lung adenocarcinoma (1); mitral valve stenosis (1); persistent truncus arteriosus (1); prostate carcinoma (1); Right ventricular hypertrophy (1); viral infection (1).